CXCR3 (C-X-C motif chemokine receptor 3)
Diseases named in the same sentence as CXCR3 in open-access papers (continued):
Sharing a sentence is not in itself a finding about the gene and the disease.
gastrointestinal infection (2 papers, 2013 to 2017). "The role of CXCR3 during infectious colitis, however, is unclear and therefore in this study, we investigated the role of CXCR3 in the regulation of the immune response during acute and chronic gastrointestinal infection, using a murine model of Salmonella enterica serovar Enteritidis." (PMID 28860493, 2017). "However, while CXCR3-GFP expression was relatively high on naïve NK cells, the GFP expression was in fact reduced during infection, suggesting lack of a role for CXCR3+ NK cells during intestinal infection." (PMID 24130498, 2013).
Gliosis (2 papers, 2016 to 2022). Gliosis is the focal proliferation of glial cells in the central nervous system. "Interestingly, the inhibition of either of the two pathways separately showed no beneficial effect, whereas the activation of either Tlr2 or Cxcr3 in the nostril paradigm was sufficient to induce gliosis." (PMID 35159329, 2022).
glomerular diseases (2 papers, 2005 to 2024). "The molecular activity of anti-ETAR and anti-CXCR3 antibodies in specific glomerular diseases should be evaluated with molecular models." (PMID 39768675, 2024). "We are the first to assess the anti-ETAR and anti-CXCR3 antibody levels in this set of different types of glomerular diseases." (PMID 39768675, 2024). "The number of CCR5- and CXCR3-positive interstitial infiltrating cells (mainly T cells) correlates with renal function and proteinuria in glomerular diseases." (PMID 16200331, 2005).
gout (2 papers, 2016 to 2025). A condition characterized by painful swelling of the joints, which is caused by deposition of urate crystals. "In our present study, expression levels of CXCL10 and CXCR3 were found to be elevated in SF of patients with PsA as compared with patients with OA and those with gout." (PMID 27964744, 2016). "CXCR3 was 5.3-fold greater (p = 0.011) in patients with PsA than in patients with OA, 32.3-fold greater (p = 1.2 × 10−6) than in patients with gout, and 3.9-fold greater (p = 0.02) than in patients with RA." (PMID 27964744, 2016). "A recent study showed that γδ2T cells may also migrate to the synovial fluid of AGA patients by interacting with chemokine receptors (CXCR3) and secreting pro-inflammatory cytokines (IL-17) to participate in the mechanism of gout." (PMID 40606658, 2025). "Indeed, similar to what we saw in CXCL10 and CXCR3 levels, we observed that mRNA expression and protein levels of IL-17A were comparable between PsA and RA samples, in accordance with reports in the literature, and significantly higher than in OA and gout SF samples." (PMID 27964744, 2016).
inflammatory skin disease (2 papers, 2017 to 2023). Inflammatory skin disorders covers a broad category that includes many conditions ranging in severity, from mild itching to grave medical health complications These disorders are common in people of all ages and races. "The IFN-γ-induced chemokines CXCL9 (chemokine C-X-C motif ligand 9), CXCL10, and CXCL11 recruit Th1 cells by binding to CXCR3 (chemokine C-X-C motif receptor 3) on the cell surface and significant infiltration of Th1 cells are seen in inflammatory skin diseases." (PMID 36742296, 2023).
intestinal tumors (2 papers, 2018 to 2020). "Tregs reduce endothelial CXCL10 production and inhibit T-cell migration into tumours, and CXCR3-mediated signalling is crucial for lymphocyte accumulation in intestinal tumours." (PMID 32680511, 2020). "In conclusion, we have shown that CXCR3 signalling is crucial for T-cell migration into intestinal tumors." (PMID 29671006, 2018). "In conclusion, this study demonstrates that Treg reduce endothelial CXCL10 production, inhibit T-cell migration into tumors and that CXCR3 mediated signalling is crucial for lymphocyte accumulation in intestinal tumors." (PMID 29671006, 2018). "Our previous study indicated that CXCR3-mediated chemotaxis may be an important means of T-cell recruitment into intestinal tumors as Treg depletion increased the production of CXCL9 and CXCL10 selectively in the tumors." (PMID 29671006, 2018). "Furthermore, T cells migrate into intestinal tumours through CXCR3." (PMID 32680511, 2020). "Furthermore, we were able to demonstrate that T cells use CXCR3 to migrate into intestinal tumors." (PMID 29671006, 2018). "This is the first time CXCR3 has been shown to be non-redundant for CD4+ T-cell migration into intestinal tumors, even though earlier results have indicated that CXCL9 and CXCL10 significantly correlate to disease free survival of CRC patients, and also to the recruitment of memory T cells." (PMID 29671006, 2018).
intracerebral hemorrhage (2 papers, 2025). A cerebrovascular disorder characterized by bleeding into one or both cerebral hemispheres including the basal ganglia and the cerebral cortex. "Our study demonstrates that AMG487-mediated inhibition of CXCR3 maintains blood–brain barrier integrity and enhances both short-term and long-term neurological deficits after intracerebral hemorrhage by suppressing the cGAS-STING/AIM2 signaling pathway in mice." (PMID 40781073, 2025).
itch (2 papers, 2019 to 2021). "To further verify the contribution of CXCR3 to AEW-induced pruritus of mice, we examined the expression of spinal CXCR3 at a series of time points." (PMID 35095512, 2021). "Additionally, we demonstrate a novel role of CXCR3 signaling in MC903-induced itch." (PMID 31631836, 2019). "Administration of a CXCR3 antagonist alleviated the itch behavior in dry skin model mice stimulated with acetone and diethyl ether followed by water (AEW), and Cxcr3−/− mice showed attenuated scratching in chronic itch models of dry skin and ACD." (PMID 35095512, 2021).
kidney cancer (2 papers, 2021 to 2022). Primary or metastatic malignant neoplasm involving the kidney. "CXCR3 mediates the directional movement of kidney cancer cells, which promotes the metastasis of kidney cancer cells, so CXCR3 positivity indicates a poor prognosis." (PMID 36479091, 2022).
Listeria infection (2 papers, 2021). "CXCR3 blockade eliminated decidual CD8+ T cell infiltration and protected against in utero fetal infection and immunopathogenesis in a murine model of Listeria infection." (PMID 34394129, 2021).
Lyme disease (2 papers, 2014 to 2016). Lyme disease (named after the towns in the USA where the disease was first identified) is a bacterial infection caused by Borrelia burgdorferi. "High CCR5 expression has been observed on csf CD4+ and CD8+ lymphocytes in neuroborreliosis, where it was also co-expressed with CXCR3." (PMID 26906062, 2016). "We reasoned that high serum levels of these chemokines may drive T cells into inflamed tissues and as a result levels of CXCR3 expressing T cells may be altered during acute Lyme disease." (PMID 24740099, 2014). "Levels of CXCR3+ CD4 T cells were determined by polychromatic flow cytometry, and found to be significantly lower in the blood of patients with acute Lyme disease versus controls." (PMID 24740099, 2014).
MALT lymphoma (2 papers, 2022 to 2024). An indolent, extranodal type of non-Hodgkin lymphoma composed of small B-lymphocytes (centrocyte-like cells). "Furthermore, CXCR3, CXCR4, and CXCR5 have been implicated in the pathogenesis of MALT lymphoma." (PMID 39451532, 2024).
mesothelioma (2 papers, 2020 to 2023). A usually malignant and aggressive neoplasm of the mesothelium which is often associated with exposure to asbestos. "Asbestos reduced IP-10 production in T cells, which may have an impact on mesothelioma cells since IP-10 is the ligand for CXCR3." (PMID 32977478, 2020). "We also found strong positive correlations between XCR1 and CXCR3 in a variety of tumors, including SKCM, UVM (uveal melanoma), SARC, MESO (mesothelioma), PCPG, BRCA, CHOL (cholangiocarcinoma), and OV." (PMID 37895310, 2023).
myelofibrosis (2 papers, 2022). A partial or complete replacement of the bone marrow stroma by fibrous tissue. "We speculate if we can find lower CXCR3 expression in MPNs, particularly myelofibrosis and if differences are seen between MPNd and MPNn." (PMID 35709177, 2022). "However, the known receptors for CXCL4, CXCR3, and CCR1 are not expressed on bone marrow MSCs, suggesting that CXCL4 acts in an indirect fashion to induce myelofibrosis." (PMID 35439167, 2022).
ocular hypertension (2 papers, 2012 to 2021). Abnormally high intraocular pressure. "In models of ocular hypertension, antagonism of CXCR3 reduces IOP, increases AqH outflow, reduces inflammation and reduces apoptosis of TM and retinal cells." (PMID 33414477, 2021). "In contrast, administration of a selective CXCR3 antagonist in a rat model of ocular hypertension decreases intraocular pressure, prevents retinal neurodegeneration, and preserves visual function." (PMID 22675496, 2012).
ocular toxoplasmosis (2 papers, 2013 to 2015). Ocular toxoplasmosis is an infection in the eye caused by the parasite, Toxoplasm a gondii. "Cxcr3 signaling is required for recruitment of cytotoxic T cells in West Nile virus encephalitis, and in the eye, Cxcl10 mediates Th1 T cell trafficking in response to chronic ocular Toxoplasmosis." (PMID 25595590, 2015). "Additionally, a study of ocular toxoplasmosis revealed that T cells infiltrating the eye during infection express CXCR3 and produce IFN-γ." (PMID 24130498, 2013).
pancreatitis (2 papers, 2021 to 2024). Inflammation of the pancreas. "The CXCL10/CXCR3 signaling axis has been implicated in generating inflammation in various diseases including pancreatitis." (PMID 34328416, 2021). "Thus, the proinflammatory capacity of pDCs and CXCR3+CCL25+ T cells during the mature phase of AIP is much greater than that of cDCs and CXCR3+CCL25+ T cells during the early phase of AIP, and this greater capacity translates into a greater potential to support a more robust pancreatitis." (PMID 39264798, 2024).
Pleural effusion (2 papers, 2011 to 2020). The presence of an excessive amount of fluid in the pleural cavity. "The absence of an increased number of CXCR3+ cells in the parietal pleura of subjects with PLTB is in keeping with previous data obtained in pleural effusions from patients with active PLTB." (PMID 21829471, 2011).
primary progressive multiple sclerosis (2 papers, 2020 to 2024). A multiple sclerosis that is characterized by steady worsening of neurologic functioning, without any distinct relapses or periods of remission. "CD4+CCR5+ T cells were shown to have higher susceptibility to apoptosis in primary progressive multiple sclerosis and visceral leishmaniosis compared to CD4+CXCR3+." (PMID 32751139, 2020). "However, CCR5+, CXCR3+, CCR6+ and CCR4+ cells within the CD4+ CD45RA− memory T-cell pool of the CSF of OCR-treated people with primary progressive multiple sclerosis were all depleted for CD20dim T cells, which was not the case for the CD8+ memory T-cell pool." (PMID 38385000, 2024).
Salmonella Infections (2 papers, 2024). Infections with bacteria of the genus SALMONELLA. "In Salmonella infection, the CXCR3 axis controls dissemination of bacteria." (PMID 39534703, 2024).
SARS-CoV infection (2 papers, 2016). "Cxcr3, Ido1, and Ptgs2 were also selected based on prior interest in identifying critical mediators of the immune/inflammatory response not previously known to influence SARS-CoV infection." (PMID 27663205, 2016).
schistosomiasis (2 papers, 2012 to 2016). An infectious disease caused by parasitic trematodes of the genus Schistosoma that colonize human blood vessels and release eggs that can cause granulomatous reactions leading to acute (swimmer's itch or acute schistosomiasis syndrome) or chronic disease. "In most cases, Tregs migrate to the Th1-infiltrated liver and the lower levels of CXCR3+ Tregs in the blood of patients with severe schistosomiasis suggest that decreases in Treg migration sites of inflammation may aggravate the disease." (PMID 26731721, 2016). "These and our findings suggest that the small proportion of CXCR3+ eTregs in individuals with severe schistosomiasis may impair the influx of eTregs into the liver, thereby contributing to HF." (PMID 26731721, 2016). "Therefore, target on CXCR3 might become a prospect therapy in different stages of the schistosomiasis." (PMID 22905138, 2012).
squamous cell carcinoma (2 papers, 2012 to 2021). A carcinoma arising from squamous epithelial cells. "Moreover, when analyzing inflammatory burden to survival, it reveals that higher infiltration of CD3- and CXCR3-expressing cells are associated with better survival in squamous cell carcinoma." (PMID 22438899, 2012). "With concomitant active TB, NSCLC patients show a better survival outcome; especially in squamous cell carcinoma, which is associated with increased CD3- and CXCR3-expressing cells within tumor." (PMID 22438899, 2012). "The inflammatory profile nearby tumor in this condition is higher than those without TB, in terms of CD3, CXCR3 and IP-10 for squamous cell carcinoma, and CD3 and CXCR3 for adenocarcinoma." (PMID 22438899, 2012).
stable angina (2 papers, 2018 to 2023). "However, the levels of CXCL9, CXCL10, and CXCR3 remained low in patients with unstable angina, comparable to the control group and significantly lower than in patients with stable angina." (PMID 30210493, 2018).
T cell lymphoma (2 papers, 2010 to 2019). "The expression levels of CXCL10 and CXCR3 were higher in patients with AOSD than in those with T cell lymphoma, HNL, tuberculous lymphadenitis, and reactive hyperplasia." (PMID 31101882, 2019). "The CXCR3 grade was also higher in patients with AOSD than in those with T cell lymphoma, HNL, TB lymphadenitis, and reactive hyperplasia (p = 0.002)." (PMID 31101882, 2019). "Furthermore, we found that the CXCL10 and CXCR3 levels were higher in the LNs of patients with AOSD than in those of patients with T cell lymphoma, HNL, TB lymphadenitis and reactive hyperplasia." (PMID 31101882, 2019).
tongue squamous cell carcinoma (2 papers, 2022 to 2023). A squamous cell carcinoma that arises from the tongue. "Similar as TGFBI, CXCR3 is also involved in the induction of epithelial-mesenchymal transition and thus in promoting metastasis and invasion of tongue squamous cell carcinoma." (PMID 36157879, 2022). "However, CXCL9/CXCR3 axis has been reported to activate Akt signaling pathway, accompany EMT and cytoskeleton rearrangement, and promote invasion and metastasis in tongue squamous cell carcinoma." (PMID 36750966, 2023).
acute lung injury (1 paper, 2016). A condition of lung damage that is characterized by bilateral pulmonary infiltrates (pulmonary edema) rich in neutrophils, and in the absence of clinical heart failure. "The aim of this study is to investigate the role of CXCR3 and IL-10 in lipopolysaccharide (LPS)-induced acute lung injury (ALI)." (PMID 26475448, 2016).
acute pancreatitis (1 paper, 2016). An acute inflammatory process that leads to necrosis of the pancreatic parenchyma. "Indeed, knocking out the CXCR3 gene in mice with experimentally induced acute pancreatitis has been shown to attenuate acute pulmonary injury." (PMID 26475448, 2016).
acute pharyngitis (1 paper, 2022). An acute and painful inflammatory process that affects the pharynx. "Moreover, reduced CXCR3 expression observed on T cells during acute pharyngitis suggests that S. pyogenes infection promotes migration of CD4+ T cells from the blood." (PMID 35140232, 2022).
acute rheumatic fever (1 paper, 2024). "have reported that the level of CXCL10 is elevated in sera from patients with acute rheumatic fever, and CXCL10 could bind to CXCR3 of T cells to activate the release of GM-CSF from T cells." (PMID 38469144, 2024).
AIDS (1 paper, 2022). A syndrome resulting from the acquired deficiency of cellular immunity caused by the human immunodeficiency virus (HIV). "Chemokine receptors, such as CXCR3, CXCR4, CCR5, and CCR7, play a critical role in many infectious diseases, including AIDS and TB." (PMID 35712309, 2022).
alopecia areata (1 paper, 2018). Loss of scalp and body hair involving microscopically inflammatory patchy areas. "Autoimmune skin diseases such as alopecia areata (hair loss) that are associated with an IFN-γ gene signature are driven by effector T cells expressing CXCR3." (PMID 30320116, 2018). "In the acute phase of alopecia areata, hair follicle production of CXCL10 is upregulated suggesting an involvement of this chemokine in attracting CXCR3+ T cells." (PMID 30320116, 2018).
aneurysm (1 paper, 2014). Bulging or ballooning in an area of an artery secondary to arterial wall weakening. "The chemokine receptors CCR2, CCR5, and CXCR3 are associated with pathways implicated previously in aneurysm pathogenesis." (PMID 24967416, 2014).
astrocytic neoplasms (1 paper, 2013). "CXCR3-positive astrocytes were also found to be increased in the CNS of HIV-positive patients, in ischaemic infarcts and in astrocytic neoplasms." (PMID 24339874, 2013).
atopic asthma (1 paper, 2021). An asthma that is characterized by symptoms that are triggered by an allergic reaction caused by inhaled allergens such as dust mite allergen, pet dander, pollen and mold. "Polymorphisms in CXCR3 have been associated with atopic asthma." (PMID 33804792, 2021).
autoimmune myocarditis (1 paper, 2013). Autoimmune myocarditis is an autoimmune disease that affects the heart. "For example, CXCR3 directs the trafficking of antigen specific CD8 T cells that induce autoimmune myocarditis." (PMID 24155966, 2013).
cardiomyopathy (1 paper, 2019). A disease of the heart muscle or myocardium proper. "CXCL9 and its receptor, CXCR3, are associated with the progression of IHD and cardiomyopathy." (PMID 31083544, 2019).
carditis (1 paper, 2025). "From a translational perspective, IL-6 and IL-8 may serve as potential diagnostic biomarkers, while targeting IL-1β or CXCR3-dependent signaling could represent therapeutic avenues to mitigate inflammation associated with carditis." (PMID 41305420, 2025).
Chagas cardiomyopathy (1 paper, 2016). A disease of the cardiac muscle developed subsequent to the initial protozoan infection by trypanosoma cruzi. "Derived allele at rs3921 and CXCL9 rs10336 also turned out to boost CXCR3 expression, in addition to that of the respective genes, in patients with severe progression of Chagas cardiomyopathy." (PMID 27551316, 2016).
Chagas disease (1 paper, 2020). A parasitic infection caused by Trypanosoma cruzi. "Overall, CXCR3 molecule seems to be an important molecule to be explored during vaccine against Chagas disease strategies." (PMID 32574175, 2020). "We have demonstrated that CXCR3 is expressed in specific CD8+ T cells after Trypanosoma cruzi infection, which induced Th1 responses with high levels of IFN-γ cytokine." (PMID 32574175, 2020).
cholangitis (1 paper, 2018). An acute or chronic inflammatory process affecting the biliary tract. "In this study, by using the CD25−/− mouse model for both cholangitis and colitis we found increased expression of CXCR3 on T cells and increased levels of the CXCR3 ligands in the liver and colon in comparison to the controls." (PMID 29868034, 2018). "For cholangitis, based on the expression patterns of PD-1 and CXCR3 on the different hepatic T cell subsets, we speculated that CXCR3 might regulate the balance between effector and memory CD8+ T cell populations." (PMID 29868034, 2018).
chorioamnionitis (1 paper, 2025). A morphologic finding indicating inflammation of the fetal sac membranes. "We could not also include data from other gestational tissues such as the placenta and foetal membranes where the CXCR3 chemokines are usually detected in abundance during chorioamnionitis and other chronic inflammatory lesions." (PMID 40140683, 2025).
chronic allograft nephropathy (1 paper, 2021). "We previously reported glomerular infiltration by CXCR3+ ICOS+ activated T cells in chronic allograft nephropathy with TG." (PMID 34207555, 2021).